PIK3CA (phosphatidylinositol-4,5-bisphosphate 3-kinase catalytic subunit alpha)
Diseases named in the same sentence as PIK3CA in open-access papers (continued):
Sharing a sentence is not in itself a finding about the gene and the disease.
tumor (continued). "Inhibition of PIK3CA can cause tumor regression in nude mice." (PMID 35769153, 2022). "This study aims to investigate the concordance rate of NGS and RT-PCR in detecting PIK3CA mutations and to evaluate whether primary tumor samples would be able to recapitulate the mutational status of the metastases." (PMID 36428975, 2022). "Indeed, the authors found RAS family and PIK3CA mutations in the circulating tumor DNA of the majority of refractory patients to HER2 inhibitors." (PMID 36556139, 2022). "For example, PIK3CA mutations are intermediate events and are commonly found in tumor subclones (21 of 29 mutations are subclonal), which may account for the variable responses to emerging PIK3CA therapies." (PMID 35993362, 2022). "Preclinical data using an in vitro model suggested that pictilisib can significantly reduce the tumor cell viability by inducing G1 cell arrest and apoptosis in multiple UC cell lines harboring either the PIK3CA mutation alone or with a co-existing NRAS mutation." (PMID 35326708, 2022). "The analysis of overall survival regarding PIK3CA gene expression favours mutated tumours." (PMID 35171329, 2022). "PIK3CA mutations lead to increased proliferation, reduced apoptosis, and tumor invasion." (PMID 35780223, 2022). "Similarly, knockout of p85β in H460 cells, which harbor a PIK3CA E545K mutation, reduced cell proliferation, colony formation, and xenograft tumor growth." (PMID 35418124, 2022). "Similarly to ESR1 mutation assessed with ctDNA, testing for PIK3CA mutations in ctDNA is concordant with the testing of tumor tissue and the prediction of alpelisib efficacy." (PMID 36077738, 2022). "In these 16 cases, PIK3CA E542K, E545K, and H1047R mutations in the tumor were mutually exclusive." (PMID 34172890, 2021). "UCEC patients with high PIK3CA had shorter survival time because PIK3CA could change the tumor immune microenvironment by altering the fraction of tumor-associated neutrophils." (PMID 34901000, 2021). "PIK3CA mutations were detected in archival tumour of six participants (50%)." (PMID 33799597, 2021). "This retrospective study included 55 LAIBC patients, among which 25.5% had PIK3CA-mutated tumours." (PMID 34911971, 2021). "Interestingly, other comutant alterations included additional alterations in NRAS in 1 tumor, a rare A18T mutation (7.1%); PIK3CA in 2 tumors (16.7%); and EGFR in 1 tumor, also a rare D761N mutation (7.1%)." (PMID 34063999, 2021). "Moreover, in women, there was also an association between mutations in AKT1 (CA > TG, p = 0.01), PIK3CA (A > G, p = 0.02) and BRIP (T > C, p = 0.02) genes with tumor recurrence, highlighting a highly pathogenic variant in PIK3CA gene, according to CLINVAR." (PMID 34680380, 2021). "In HR+, HER2− MBC patients with resistance to CDK4/6 inhibitors plus endocrine treatment, PIK3CA mutation testing on tumor tissue or circulating tumor cells is justified to select patients who could potentially benefit from alpelisib." (PMID 34885105, 2021). "This may prove especially true for PTEN which acts as the only tumor suppressor in the PIK3CA pathway and is exemplified by the variety of PTEN mutations found in several cancers." (PMID 34943931, 2021). "Tumor sequencing was performed on samples from 27 elderly patients to identify PIK3CA mutations." (PMID 34287479, 2021). "The PIK3CA gene is a proto-oncogene highly mutated in many tumor types." (PMID 34680380, 2021). "The gene most frequently altered was PIK3CA (two variants in cell/tumor 2, one in cell/tumor 5)." (PMID 33917394, 2021). "PIK3CA mutations were associated with large tumor size and aggressive clinical behavior." (PMID 33525726, 2021). "Moreover, FSCN1 is related to apoptosis-associated genes, and its expression level is positively associated with YWHAZ specifically in tumor tissues and cells with PIK3CA alterations." (PMID 34249689, 2021).
tumor (continued). "In Cox proportional hazards regression analysis, the factors significantly associated with survival included the presence of PIK3CA mutation in circulating DNA collected before treatment, stage, tumor size and recurrence (p = 0.015, p = 0.0034, p = 0.016 and p < 0.0001, respectively)." (PMID 34203201, 2021). "Notably, PIK3CA circulating tumour DNA mutations were detected in the plasma of all trial participants, including those who tested negative for the mutation in tissue." (PMID 33799597, 2021). "Recent evidence suggests that PIK3CA mutation status may impact the tumour immune microenvironment in ER-positive breast cancer, and this is therefore likely to be important in ILC." (PMID 33413533, 2021). "The concordance rate of PIK3CA mutation status between cfDNA and tumor tissue was 83.1%." (PMID 34453076, 2021). "As for the tumor counterpart, tissue derived from P12 harbored a PIK3CA missense mutation (chr3_178928067_C_A), two APC stop-gain mutations (chr5_112173917_C_T; chr5_112175951_ G_T), a PTEN stop-gain mutation (chr10_8972066_8972078dup), and a KRAS missense mutation (chr12:_25398284_C_A)." (PMID 34154611, 2021). "Seven tumours had enough tissue to analyse PIK3CA mutation status after neoadjuvant chemotherapy." (PMID 34911971, 2021). "HPVs were more frequently episomal in PIK3CA mutated tumours (p = 0.023)." (PMID 33191407, 2021). "Tumor cells with PIK3CA mutations could be targeted by the PI3K inhibitor alpelisib plus fulvestrant in ERα positive tumors." (PMID 34885114, 2021). "This prognostic impact varied according to the tumor PIK3CA mutational status." (PMID 33673133, 2021). "In addition, class 3 weights were associated with FGFR3 and PIK3CA mutations, as well as lower tumor stage and grade." (PMID 33863885, 2021). "A possible explanation for the divergent results of the studies concerning the PIK3CA mutational status, aspirin use, and overall survival could be that the patient cohorts of the studies differed with regard to further molecular tumor markers." (PMID 34638442, 2021). "In addition, we also showed that ARID1A and PIK3CA mutations frequently co-occur in UCEC tumor samples." (PMID 34941867, 2021). "Among OCCC cases with PIK3CA mutation in the tumor, only one case had homogeneous PIK3CA mutation in the epithelial component of the tumor and a single hotspot mutation with MAF ≥ 15%, consistent with the tumor, in the eutopic endometrial glandular epithelium (case h)." (PMID 34172890, 2021). "Notably, half (n = 3) of these also had >500 copies/mL of a second PIK3CA mutation detectable in their baseline ctDNA sample, although in lesser quantities than the tumour mutation." (PMID 33799597, 2021). "Significantly poorer outcomes were observed for patients with PIK3CA mutated tumours as compared to patients with PIK3CA wild-type tumours (HR 2.0, 95% CI 1.0–3.9, p = 0.045) although this did not remain significant in a multivariate analysis adjusting for clinicopathologic variables." (PMID 33804510, 2021). "Only 6 of 25 (24%) cases had the same PIK3CA mutation in the tumor and Pap smear or plasma." (PMID 34172890, 2021). "Interestingly, all six patients with PIK3CA-wildtype archival tumour had detectable circulating PIK3CA mutations in their baseline plasma ctDNA." (PMID 33799597, 2021). "PIK3CA was mutated in different tumor types (SNSCC, SNEC, SNUC, SNAC and ACC)." (PMID 34885191, 2021).
tumor (continued). "In addition, recent studies have shown that PI3K inhibitors (i.e., alpelisib) have significant clinical activity against PIK3CA-mutated luminal breast cancers, including ET-resistant tumor cells." (PMID 33672204, 2021). "Five out of 15 tumours had mutations in PIK3CA of which 60% of patients had a PR or CR." (PMID 33204026, 2021). "Some studies also hypothesised that PIK3CA mutations may play a pivotal role in tumour initiation and malignant transformation." (PMID 34842356, 2021). "Indeed, when a mutation (e.g., PIK3CA) is usually present only at an average of one copy/tumor cell, tumor HPV DNA is present at 100–1000 copies/tumor cell, thereby increasing the amount of ctDNA releases in plasma after cell death." (PMID 34359795, 2021). "In addition, using microarray analysis, we also identified the overexpression of LOX and PTX3 in KARS and PIK3CA mutant cell lines compared to the HMOsisEC10 cells, which was associated with the aggressive behavior of the benign tumor." (PMID 34202354, 2021). "PIK3CA mutations were identified in 5/40 (12.5%) HER2-negative tumours." (PMID 33933113, 2021). "Indeed, Notch1ICD cooperated with both Pik3ca alleles to significantly reduce tumor latency and increase tumor number per mouse." (PMID 34475389, 2021). "PIK3CA mutation was detected by next-generation sequencing (NGS) of a tumor gene-panel." (PMID 32632138, 2020). "Of the 8 ESCC tumor tissues (12.5%) with PIK3CA mutation, 2 (25.0%) were PD-L1-positive." (PMID 33054840, 2020). "Furthermore, the observed effect modification of PIK3CA mutation status by aspirin use highlights the important limitations to current knowledge about the tumor effects of aspirin." (PMID 32326897, 2020). "Moreover, in patients with advanced HR+/HER2−breast cancer, 28% of PIK3CA mutations were identified in circulating tumor DNA." (PMID 33375317, 2020). "It has been demonstrated that the activation of the PI3-kinase pathway might enhance the invasive ability of tumor cells into lymph nodes and PIK3CA mutation is related with the loss of PTEN which inhibits cell migration." (PMID 32908885, 2020). "The case report described how the PI3K/Akt and Ras-MAPK pathways play a role in regulating immune evasion and that the patient’s tumor harbored a hyperactivating PIK3CA mutation (H1047R), which may have influenced tumoral PD-L1 expression." (PMID 33148288, 2020). "Changes in these related genes and signaling pathways promote cell proliferation and inhibition of apoptosis, leading to early-stage metastasis of tumor cells, such as mutation, methylation or expression of PIK3CA, PTEN, AKT and other genes in the PI3K/AKT/mTOR pathway." (PMID 33186389, 2020). "Third, the PI3-kinase pathway activation may enhance the invasion of lymph nodes by tumor cells and PIK3CA mutation is related with the loss of PTEN which inhibits cell migration." (PMID 32908885, 2020). "Previous studies have revealed that in AR+ TNBC, PIK3CA kinase mutations were more common and that targeting AR alone could potentially enhance tumor growth." (PMID 32982970, 2020). "Determinations of tumor PIK3CA mutation status may have additional implications for future research or treatment strategies." (PMID 32637176, 2020). "Such a synergic anti-tumor effect suggested PIK3CA mutation and FGFR aberration might be independent to each other." (PMID 31980592, 2020).
tumor (continued). "The number of copies of the PIK3CA gene was associated with the tumor grading (r = 0.208)." (PMID 33287350, 2020). "The observations of less than 5% VAF of the IDH1 mutation in cases 3, 5, and 6 in a contexts of 51%‐70%, 31%‐50%, and 41%‐60% estimated tumor cellularity and 33%, 13%, and 18% VAF of the coexisting EGFR, KRAS, or PIK3CA mutation suggest presence of IDH1 mutation in a tumor subpopulation." (PMID 32333643, 2020). "As expected, BMP7v in combination with taselisib significantly reduced the size of tumor xenografts generated by the injection of PIK3CA-mutated CR-CSCs, suggesting the necessity to simultaneously add a PI3K inhibitor in the presence of enhanced activation of the PI3K/AKT pathway." (PMID 31591478, 2020). "PIK3CA-mutated tumor xenografts display resistance to the combination of BMP7v and chemotherapy." (PMID 31591478, 2020). "The mutation of PIK3CA is a carcinogenic activator of the Akt pathway, which could promote cell proliferation and tumor growth." (PMID 32596290, 2020). "Forty-two tumor samples were available for genetic testing and 32 (74%) had a PIK3CA mutation." (PMID 33148288, 2020). "Importantly, it was recently shown in the SOLAR-I trial that the PIK3CA mutation status as determined by the use of circulating tumor DNA predicts response to alpelisib." (PMID 32934773, 2020). "Tumor DNA sequencing detected a somatic variant of PIK3CA Q546R." (PMID 32669548, 2020). "Due to the low frequency of RAS, PIK3CA or PTEN mutations in tumor tissue, a small number of patients with these mutations had been analyzed in other studies; hence, the clinical significance of these mutations remains unclear." (PMID 32823871, 2020). "Formalin-fixed, paraffin-embedded primary tumor specimens underwent polymerase chain reaction (PCR) PIK3CA testing for two hotspot mutations in exon 9, one hot-spot mutation in exon 20, and fluorescence in situ hybridization (FISH) analysis for PIK3CA amplification." (PMID 30867034, 2019). "BYL719 (alpelisib), an oral selective PI3Kα isoform inhibitor, exhibited dose-dependent antitumor activity in tumor xenograft models, particularly models with mutated or amplified PIK3CA, highlighting the potential antitumor activity of alpelisib in patients with PIK3CA-altered tumors." (PMID 30782187, 2019). "Notably, the mutation rate of PIK3CA in tumor DNA and/or ctDNA of HR‐positive patients was 48.08%, while a much lower rate was observed for HR‐negative patients (15.79%; P = 0.014)." (PMID 30672098, 2019). "However, the co-presence of alterations in MAP3K1, a putative tumor suppressor, with PIK3CA mutations was associated with a significant clinical benefit rate (CBR)." (PMID 31552290, 2019). "PIK3CA mutations were detected in tumor tissue, and the primary endpoint of the study was PFS." (PMID 31450618, 2019). "Multivariate analysis was also performed with baseline prognostic variables including age, gender, tumor location, differentiation, and PIK3CA E545K mutation indicating that PIK3CA E545K mutation was a detrimental factor for OS (HR = 6.497, 95% CI: 2.859-14.768, p < 0.021." (PMID 32099598, 2019). "However we detected individual somatic variants in known oncogenes (e.g. PIK3CA) and tumor suppressors (e.g. CDC20)." (PMID 30870501, 2019). "Of note, in addition to a mutation in the cancer driver Kras we detected two mutations in PI3K subunits Pik3r1 and Pik3ca and a deactivating stop-gain mutation of tumor suppressor Pten, which regulates PI3K by dephosphorylating the lipid signaling intermediate PIP3 to PIP2." (PMID 30262843, 2019). "Therefore, this nontargeted therapy seems to be ineffective to reduce the CTC/tumor burden in metastatic BrCa patients harboring PIK3CA hotspot mutations." (PMID 31254443, 2019). "Larger clinical trials in specific tumor types may be required to determine the effect of PIK3CA mutation on response to neratinib in HER2-driven cancer." (PMID 31141894, 2019).
tumor (continued). "In addition, PTEN is a tumor suppressor and is modified by methylation and mutation to induce the reduction of its expression, thus boosting the activity of the downstream PIK3CA and AKT1." (PMID 31126066, 2019). "This PTEN/ARID4B/PIK3CA signature robustly stratified patients into those at high versus low risk for tumor recurrence (HR = 4.58, P = 0.006 in the GSE40272 dataset; HR = 3.23, P = 0.002 in the GSE21032 dataset; HR = 1.51, P = 0.025 in the TCGA dataset; Statistical analysis: log-rank test)." (PMID 31551414, 2019). "In this analysis evaluating the predictive role of longitudinal ctDNA assessment in the PALOMA-3 study, we show that early circulating tumor DNA dynamics with truncal PIK3CA mutations predict sensitivity to palbociclib in advanced hormone receptor-positive breast cancer." (PMID 29497091, 2018). "The difference in the CCFs of these two driver mutations postulated that the EGFR mutation might drive tumor initiation, whereas the PIK3CA mutation contributed to tumor progression." (PMID 29738578, 2018). "PIK3CA gene mutations were also detected in genomic DNA extracted from tumor blocks." (PMID 29707142, 2018). "In addition, some of the mutation occurrences were tumor type-specific, e.g., PIK3CA mutations showed co-occurrence with FAT4 mutations with a high frequency in BLCA, but mainly co-occurred with PTEN mutations in UCEC." (PMID 29697365, 2018). "However, the significant association between PIK3CA mutation and tumor differentiation should be interpreted with caution because of the small sample size (two studies comprising 386 patients) and need more studies to confirm." (PMID 29484141, 2018). "Moreover, while expression of oncogenic PIK3CA in luminal progenitors causes a multilineage differentiation at the early stage of tumor initiation, its expression in unipotent BCs gives rise to functional LCs." (PMID 29853913, 2018). "PIK3CA p.E545K is a frequent somatic mutation in HNSCC tumours." (PMID 30501041, 2018). "Our results here demonstrate that early suppression of ctDNA predicts long-term outcome substantially earlier than changes in tumor size, when truncal mutations such as PIK3CA are tracked in plasma, in the setting of palbociclib with fulvestrant in advanced hormone receptor-positive breast cancer." (PMID 29497091, 2018). "Five out of 6 patients with a PIK3CA mutation in either primary tumor or relapse tissues exhibited one of the 3 “Hotspot” mutations shown to cause gains in protein enzymatic function and induce oncogenic transformation (E542 and E545 in the helical domain and H1047 in the kinase domain)." (PMID 30167082, 2018). "However, lower frequency of HER2/BRAF/PIK3CA mutations was observed in biopsy samples with <20% tumor cellularity as compared to those with ≥20% tumor cellularity." (PMID 29518290, 2018). "That is, the mutation of PIK3CA occurs early in the tumor progression." (PMID 30540749, 2018). "In this study, we evaluate whether the fluctuations in the fraction of PIK3CA mutant allele correlates with tumor response according to RECIST criteria and tumor markers quantification." (PMID 28330468, 2017). "PIK3CA mutation detected in circulating tumor DNA (ctDNA) was predictive for a buparlisib efficacy." (PMID 28725277, 2017).